TAF11L10 (TATA-box binding protein associated factor 11 like 10)
Tractability: No criterion of Open Targets' tractability assessment is met for any kind of drug.
Gene: Protein-coding gene on chromosome 5 (17,597,232 to 17,597,828, reverse strand). Ensembl gene ENSG00000284356.
Gene Ontology:
Molecular function: RNA polymerase II general transcription initiation factor activity; protein heterodimerization activity
Biological process: RNA polymerase II preinitiation complex assembly; transcription initiation at RNA polymerase II promoter
Cellular component: transcription factor TFIID complex; nucleus
Homologues: Orthologues: tropical clawed frog taf11 (45% identical), zebrafish taf11 (45% identical), Drosophila melanogaster Taf11 (42% identical), Caenorhabditis elegans taf-11.1 (33% identical), Caenorhabditis elegans taf-11.2 (27% identical). Paralogues in human: TAF11L5 (100% identical), TAF11L6 (100% identical), TAF11L7 (100% identical), TAF11L8 (100% identical), TAF11L3 (99% identical), TAF11L4 (99% identical), TAF11L9 (99% identical), TAF11L13 (95% identical), TAF11L2 (92% identical), LINC02218 (88% identical), TAF11L12 (87% identical), TAF11L11 (85% identical), and 2 more.